BCL11B (BCL11 transcription factor B)
Diseases named in the same sentence as BCL11B in open-access papers (continued):
Sharing a sentence is not in itself a finding about the gene and the disease.
skin cancer (1 paper, 2020). "Few reports of human studies are available regarding a potential role of Bcl11b in skin cancer." (PMID 33363142, 2020).
T cell deficiency (1 paper, 2024). "A previous study reported a patient with severe T cell deficiency harboring a de novo BCL11B heterozygous variant, causing a replacement of the N441 residue within the second ZnF with a K, resulting in the BCL11BN441K variant protein." (PMID 38495886, 2024).
teratoma (1 paper, 2022). A non-seminomatous germ cell tumor characterized by the presence of various tissues which correspond to the different germinal layers (endoderm, mesoderm, and ectoderm). "Of note, Bcl11b KD iPS cell lines were capable of forming three germ layers in teratoma, indicating that Bcl11b loss is compatible with the acquisition of multilineage differentiation potential." (PMID 36075976, 2022).
Tremor (1 paper, 2023). An unintentional, oscillating to-and-fro muscle movement about a joint axis. "A subset of animals developed symptoms reminiscent of neurodevelopmental phenotypes, such as tremor, consistent with a function of Bcl11b in brain development." (PMID 36950387, 2023).
triple-negative breast carcinoma (1 paper, 2020). An invasive breast carcinoma which is negative for expression of estrogen receptor (ER), progesterone receptor (PR), and human epidermal growth factor receptor 2 (HER2). "The same is true for BCL11B, IKZF3, and KLRC4, which have very recently been linked to a prognostic immunogenic signature of triple-negative breast cancers." (PMID 32605588, 2020).
tumor (70 papers, 2007 to 2026). "The therapeutic relevance of this regulatory axis is underscored by experiments showing that inhibition of NF-κB/Jak-Stat signaling with TPCA-1 can rescue the aging phenotype and significantly reduce tumor incidence in Bcl11b-deficient models." (PMID 40862719, 2025). "This suggests that a differentiation arrest triggered by BCL11B deficiency can represent an important step toward tumor development." (PMID 39955618, 2025). "Early studies on BCL11B role in T-cell malignancies, mostly based on the deletions and mutations, suggested its tumor suppressor function." (PMID 39295773, 2024). "As such, kilo-/megabase deletions in a Bcl11b-linked non-coding region triggered aggressive malignancies, with allele-specific tumor spectra reflecting gradual gene dysregulations through modular and cell-type-specific enhancer activities." (PMID 36950387, 2023). "For instance, the transcription factor BCL11B has been shown to be a tumor suppressor that is frequently mutated in lymphoid malignancies." (PMID 36230837, 2022). "In mice, the ablation of Bcl11b in the adult epidermis led to an increased risk of tumor formation upon treatment with acute doses of TPA (12-O-tetradecanoyl phorbol-13-acetate) or UVB." (PMID 33363142, 2020). "Four out of six tumours presented Tcra/d linked amplification, and all six showed chromosome 12 deletion with Bcl11b loss." (PMID 32060399, 2020). "Suppression of Bcl11b by RNA interference (RNAi) causes apoptosis of these tumour cells, possibly due to a decrease of a cell-cycle inhibitor, p27, and an anti-apoptotic protein, BCL-xL." (PMID 25408871, 2012). "Bcl11b was initially identified as a tumour suppressor gene in T cells, because loss of heterogynous (LOH) contributed to the formation of thymic lymphomas in γ–ray irradiated mice." (PMID 25408871, 2012). "Bcl11b has been suggested to function as tumor suppressor in cells, primarily based on human loss of homozygosity (LOH) studies." (PMID 19399189, 2009). "In addition, we identify a master transcription factor, Bcl11b, that comprehensively suppresses both early and late senescence programs and find that loss of Bcl11b expression dramatically accelerates aging and tumor formation." (PMID 38886378, 2024). "As Bcl11b is critical for T cell development, the observed effect of Bcl11b heterozygosity on tumor formation may possibly attribute to T cell deficiency." (PMID 39433900, 2024). "While some studies postulated that BCL11B acted as a tumor suppressor and that inactivating mutations played a role in tumor development, others, including our studies, suggested BCL11B as being an oncogene and its downregulation resulting in apoptosis of malignant T cells." (PMID 35563322, 2022). "BCL11B is linked to both embryogenesis and tumor suppression." (PMID 34287293, 2021). "Alignment of the RNAseq reads with a normal BCL11B allele sequence without HPV70 identified all the standard splice junctions of the host gene, including variable inclusion of exon 3, indicating expression of normal BCL11B transcripts in the tumor as well, possibly from normal BCL11B alleles." (PMID 31407403, 2020). "BCL11B mutations are associated with T cell proliferative disorders, even though it is arguable whether BCL11B acts as tumor suppressor or oncogene in T-ALL." (PMID 25644173, 2015). "Here we show that BCL11B possesses features which, depending on the expression level and the cellular context, could predispose it to the role of both tumor suppressor and a gene supporting survival of transformed cells." (PMID 20824091, 2010). "Interestingly, wild-type Bcl11b was able to suppress cell proliferation, whereas tumor specific point mutations and frameshift mutations in Bcl11b enhanced proliferation." (PMID 17941976, 2007). "The transition towards senescence program is governed by a stem cell factor Bcl11b, loss of which accelerates mammary aging with enhanced DMBA-induced tumor formation." (PMID 41597281, 2026).
tumor (continued). "BCL11B inhibits caspase-8 activity to block extrinsic apoptosis signaling transduction, consequently enabling tumor cells to evade immune clearance." (PMID 40547036, 2025). "Bcl11b-KO also increased immune checkpoint pathway (PD-L1 and PD-1), consistent with its role in promoting tumor formation." (PMID 38886378, 2024). "The transition towards senescence program is governed by a stem cell factor Bcl11b, loss of which accelerates mammary ageing with enhanced DMBA-induced tumor formation." (PMID 38886378, 2024). "We reasoned that if neighboring cells give rise to tumors, then WT and Bcl11b tumor cells likely have a similar phenotype." (PMID 38886378, 2024). "Very recent study on BCL11B involvement in DNA repair provided new important information on role in tumor development." (PMID 39295773, 2024). "The xenograft transplantation assays showed BCL11B KO LoVo cells exhibited impaired tumor development, with a reduction of both tumor weight and tumor size, compared to parental cells." (PMID 39433900, 2024). "The authors postulated that BCL11B is a haploinsufficient tumor suppressor that collaborates with all major T-ALL oncogenic lesions in human thymocyte transformation, although this has not been confirmed in functional studies." (PMID 39295773, 2024). "With Bcl11b set aside which has a negligible influence of CR, CR significantly decreased TLs with any of the tumor suppressors affected by such copy-neutral LOHs (i." (PMID 36662808, 2023). "Concordantly, BCL11B expression was significantly higher in both tumor and lymph node metastasis than in healthy mucosa." (PMID 34287293, 2021). "We identified BCL11B as a novel tumor suppressor in HCC that exerts inhibitory effects on cell proliferation and migration." (PMID 33093445, 2020). "Most of these joined the viral E1^E4 5′ss to the 3′ss for BCL11B exon 4, showing that viral‐host fusion transcripts were synthesized in this tumor." (PMID 31407403, 2020). "Most striking was the BCL11B region of chromosome 14, with individual tumor cells displaying from two to over 50 copies." (PMID 31407403, 2020). "In vitro and in vivo experiments confirmed BCL11B as a tumor suppressor in HCC with inhibitory effects on proliferation, cell cycle progression, apoptosis, and mobility." (PMID 33093445, 2020). "This suggests that E7, BCL11B, and the chromosome 3q amplification were all likely important genetic components that function together at least to maintain this tumor." (PMID 31407403, 2020). "Presence of the 3980 bp HPV70 DNA insertion into BCL11B was also confirmed by PCR testing for the HPV70 L1 junction in the CIN3 biopsy as well as in the tumor." (PMID 31407403, 2020). "Previous studies identified B cell leukemia/lymphoma-11b (BCL11B) as a novel tumor suppressor with impressive capacity to restrain CSC traits." (PMID 33093445, 2020). "By validating core transcripts in tumor tissues and adjacent normal tissues, we found that BCL11B showed the greatest expression differences between tumor tissues and adjacent normal tissues, which attracted our attention." (PMID 30093865, 2018). "Along transcripts whose expression levels significantly decreased in both ALV-J infected spleen and tumor tissues, BCL11B showed the greatest change." (PMID 30093865, 2018). "The target of gga-miR-219b, BCL11B, promoted tumor cell proliferation, apoptosis, migration and invasion." (PMID 28652615, 2017). "The results above showed that both gga-miR-219b overexpression and BCL11B knockdown induced tumor cell apoptosis." (PMID 28652615, 2017). "Both gga-miR-219b and BCL11B mediated tumor cell apoptosis through influencing gene expression levels in the mitochondrial and death receptor pathways." (PMID 28652615, 2017). "In this study, we verified that BCL11B was a target gene of gga-miR-219b and preliminarily investigated the function of gga-miR-219b and BCL11B in Marek’s disease tumor cell line." (PMID 28652615, 2017).
tumor (continued). "Previous investigations have demonstrated that Bcl11b is haploinsufficient for its tumour suppression effects, however in this study, mitotic recombination and non-disjunction events were also apparent at high frequency." (PMID 26125582, 2015). "Mutations or deletions of the BCL11B gene are found in 9–16% of human T-ALL where it is thought to be a haploinsufficient tumor suppressor." (PMID 23527175, 2013). "On the other hand, the haploinsufficient tumor suppressor function of the BCL11B gene has been reported in mouse and human lymphomalignancies." (PMID 23383087, 2013). "This feature qualifies BCL11B as a tumor suppressor or a gene maintaining the balance between proliferation and cell death." (PMID 20824091, 2010). "The data presented here suggest a potential role of BCL11B in tumor survival and encourage developing Bcl11b-inhibitory approaches as a potential tool to specifically target chemoresistant tumor cells." (PMID 20824091, 2010). "Furthermore, our analysis showed that the correlation between TMED10 and the microbiome gradually weakened from A to early and advanced tumor stages, while the correlation between BCL11B and the microbiome progressively increased." (PMID 41472855, 2025). "Notably, Bcl11b has been documented to function as a tumor suppressor in various cancers, aligning with the observed decrease in Bcl11b levels following Mycn overexpression in epithelial cells." (PMID 40862719, 2025). "The aim of this review is to discuss the 2 contradictory hypotheses on the function of BCL11B in T-cell neoplasms; tumor suppressor; or oncogene." (PMID 39295773, 2024). "Interestingly, a gene set enrichment assay (GSEA) showed that WT tumor cells were significantly enriched with a-Young signature genes, while Bcl11b-KO tumor cells were enriched with l-Sen genes." (PMID 38886378, 2024). "In addition, the Bcl11b-KO tumor cells themselves exhibited high levels of senescence-associated cytokine IL6 and high NF-kB activity." (PMID 38886378, 2024). "The screens across many cancer types described here provide evidence for widespread haplo- and quasi-insufficiency in tumor evolution, and we show in mouse models that even small or temporal gene expression changes of tumor suppressors, such as Bcl11b, can be oncogenic." (PMID 36950387, 2023). "Together, this observation suggests that hypermethylation of BCL11B may be considered a novel molecular hallmark of T-LGLL and corresponds to the tumor cell content." (PMID 36376973, 2022). "gga-miR-219b had a suppressive effect on tumour cells by targeting BCL11B." (PMID 36422982, 2022). "Since ITNK cells killed tumor cells in vitro and in vivo, the inhibition of BCL11B may additionally exert its anti-tumor activity by inducing normal T cells to kill the remaining malignant T cells." (PMID 35563322, 2022). "In summary, there was extensive variability in BCL11B copy number among the tumor cells." (PMID 31407403, 2020). "Moreover, primary tumor tissues of patients who suffered metastasis exhibited lower BCL11B protein levels." (PMID 33093445, 2020). "Aberrant BCL11B expression was found to influence the proliferation, migration, and invasion of the Marek’s disease tumor cell line, MSB1, suggesting that BCL11B may be involved in tumorigenesis in various animals and in neoplastic diseases." (PMID 30093865, 2018). "BCL11B monoallelic deletions or missense mutations occurred across each of the major molecular subtypes of T-ALL, which suggested that BCL11B is a haploinsufficient tumor suppressor in human thymocyte transformation." (PMID 28652615, 2017).
tumor (continued). "The occurrence of adenovirus in the tumor sections was confirmed by subsequent fluorescence in-situ-hybridization analysis and co-staining with the transcription factor Bcl11b gives evidence for the presence of the virus in infiltrating T-lymphocytes within the tumors." (PMID 23671688, 2013). "Moreover, another member of the BCL11 family, BCL11B, has been suggested as a tumor suppressor gene, acting via an increase in resistance to DNA damage." (PMID 23758992, 2013). "Interestingly, though Bcl11b is considered as a tumour suppressor gene, it is highly expressed in many human T cell tumour lines and is required for their survival." (PMID 25408871, 2012). "But in the context of a tumor tissue BCL11B could act as potential oncogene being an attractive target for therapeutic approaches." (PMID 20824091, 2010). "This indicates that elevated BCL11B could play a similar role in tumors expressing it by controlling proliferation and chemoresistance of tumor-initiating cells." (PMID 20824091, 2010). "Several human genetic studies suggest that Bcl11b could act as a tumor suppressor gene in T-cells." (PMID 33363142, 2020). "As for BCL11B, a C2H2 zinc finger transcription factor and a haploinsufficient tumor suppressor, it exerts inhibitory effects on tumor progression through a wide range of mechanisms." (PMID 35621244, 2023). "Mechanism studies revealed that BCL11B prevents cancer immune evasion by acting as a competitive endogenous RNA to upregulate MICA and MICB, which essentially control tumor immune surveillance." (PMID 35621244, 2023). "RT‐PCR revealed a significant correlation between the BCL11B and GATA6 expressions in tumor and non‐tumor tissues, and the IHC analysis supported the results in tumor tissue." (PMID 37293953, 2023). "Focally deleted regions identified the tumour-suppressor genes RHOA at 3p21, CDKN2A and CDKN2B at 9p21, RAD51B, MAX, DICER1, BCL11B, NKX2-1, CCNB1IP1 and BAZ1A at 9q33." (PMID 34980126, 2022). "In strong co-expression to BMI‐1, BCL11B (B-cell lymphoma/leukemia 11B) was identified as an additional CSC marker in HNSCC that is otherwise observed in both embryogenesis and tumor suppression." (PMID 32588101, 2021). "The faint upper band was also recovered from the tumor RT‐PCR and sequenced thus confirming the structure of HPV70 E1 spliced to exon 3B, and exon 3B spliced to exon 4 of BCL11B in the same RNA." (PMID 31407403, 2020). "The BCL11B-silenced MHCC97L cells were able to generate tumors even when only 102 cells were injected, and exhibited higher rates of tumor formation than control cells at all four dilution orders." (PMID 33093445, 2020). "Consistently, immunofluorescence of ACP histological sections revealed the expression of BCL11B and TP63 exclusively in tumour cell compartments, including clusters, palisading epithelium and stellate reticulum, but not within surrounding reactive tissue." (PMID 29541918, 2018). "B-cell chronic lymphocytic leukemia/lymphoma 11B (Bcl11b), also named Ctip2, is a C2H2 zinc finger protein, originally discovered in T lymphoblastic leukemia, and identified as a tumor suppressor in hematopoietic malignancies." (PMID 29416501, 2018). "After BCL11B inhibition, TNFSF10 was activated at the transcriptional and translational level in tumor T-cell lines such as Jurkat and huT7837." (PMID 28652615, 2017).